LEP (leptin)
Diseases named in the same sentence as LEP in open-access papers (continued):
Sharing a sentence is not in itself a finding about the gene and the disease.
Hypertension (continued). "Additionally, the adipose tissue also contributes to hypertension by their endocrine and paracrine effects on the endothelial cells by producing substances—cytokines leptin and adiponectin which have detrimental effects on the vasculature." (PMID 30212508, 2018). "These novel findings provide important evidence that HDL and leptin maybe possibly mediate the process of CYP17A1 involved in hypertension." (PMID 29338791, 2018). "Leptin-induced enhanced intracellular calcium concentration could contribute to the development of hypertension, through altering vasomotion and contributing to vascular remodelling." (PMID 28085954, 2017). "We could argue that perhaps leptin have distinct actions in HFD hypertensive animals compared to hypertension‐resistant animals." (PMID 27273815, 2016). "Leptin levels were positively correlated with prepregnancy body mass index—BMI (r = 0.57), gestational (37 or 38 weeks of gestation) BMI (r = 0.39), hypertension (r = 0.27), and hyperglycemia (r = 0.30), and negatively associated with newborns’ abdominal circumference (r = −0.25)." (PMID 27651836, 2016). "Leptin, which is released preferentially in subcutaneous adipose tissue versus visceral adipose tissue, stimulates renal sympathetic activity, eventually resulting in hypertension and glomerular hyperfiltration." (PMID 26495973, 2015). "This suggests that leptin may initiate hypertension and may contribute to changes that can maintain high blood pressure." (PMID 26617526, 2015). "The links between the different signal transducers may provide a helpful approach in developing potential therapeutic strategies to attenuate the harmful effects of hypertension and leptin on vascular remodeling." (PMID 26557089, 2015). "Leptin administration in these mice promptly induces hypertension." (PMID 25650072, 2015). "Moreover, a leptin antagonist was shown to reverse hypertension induced by leptin central overexpression and was proposed to be a novel therapeutic approach for the treatment of autoimmune diseases." (PMID 25918733, 2015). "In addition, the involvement of the RhoA/ROCK pathway and actin cytoskeleton remodeling in hypertension/leptin-induced ROS formation and vascular hypertrophy were investigated in this study." (PMID 26557089, 2015). "After adjustment for confounders, the authors concluded that free leptin surrogates are associated with masked hypertension in nonobese normoglycemic subjects." (PMID 24772364, 2014). "However, leptin levels have also been shown to be increased in patients with systemic hypertension and pulmonary arterial hypertension, independently of their body mass index." (PMID 24499246, 2014). "Taken together, these observations demonstrate in several different rodent models that leptin influences blood pressure and that hyperleptinemia in obesity might contribute to the hypertension." (PMID 24167814, 2013). "Leptin, in particular, could aggravate hypertension and endothelial damage by promoting catecholamine production." (PMID 23527185, 2013). "Furthermore, this indicates that the hypothalamus is significant in the elevation of leptin levels in the circulation of obese individuals with hypertension." (PMID 24137236, 2013). "Leptin plays a key role in regulating energy intake/expenditure, metabolism and hypertension." (PMID 23029163, 2012). "Leptin is an adipose tissue-derived hormone that has been shown to be related to several metabolic, inflammatory, and hemostatic factors involved in the development of hypertension and cardiovascular disease." (PMID 22666590, 2012). "Increased circulating concentrations of leptin are found in hypertensive animal models and humans, suggesting a possible link between hyperleptinemia, and cardiovascular dysfunction in hypertension." (PMID 20592755, 2010). "Together, it could be speculated that, in the setting of hypertension, the antiproliferative effects of leptin are overridden by the effects of Ang II, despite the hyperleptinemia." (PMID 20592755, 2010).
Hypertension (continued). "To determine whether this vascular action of leptin may be altered in hypertension, we assessed the effect of leptin on Ang II-induced proliferative response in aortic VSMCs from SHR rats." (PMID 20592755, 2010). "Although the relationship between high serum leptin and hypertension has been reported in many human studies, it is unknown if chronic hyperleptinemia affects renal function in humans." (PMID 21286276, 2010). "Serum leptin concentration may contribute to the risk of CVD by altering lipid metabolism and contributing to hypertension via the activation of the sympathetic nervous system and increasing renal sodium re-absorption." (PMID 17617917, 2007). "Additionally, adipokines and cytokines released by PRAT (such as leptin and adiponectin) may have an adjacent effect on renal function and blood pressure, participating in the onset of hypertension via humoral regulation." (PMID 40487756, 2025). "However, despite high leptin levels, many obese individuals experience leptin resistance, and high circulating leptin levels can lead to endothelial dysfunction, which is a precursor and major contributor to hypertension, atherosclerosis, and coronary artery disease." (PMID 41149623, 2025). "Additionally, obesity favors is a risk factor of hypertension (HTN), which can result in IR or hyperinsulinemia, elevated leptin, enhanced renal sodium reabsorption, and improved functioning of the sympathetic nervous system and renin-angiotensin-aldosterone system activity." (PMID 40756600, 2025). "Leptin has also been highlighted as a functional risk factor because the presence of this macromolecule worsens OSA and has been demonstrated to affect sleep architecture, particularly in patients with hypertension, as it affects satiety, glucose levels, and fatty acid metabolism." (PMID 38180683, 2024). "Thus, leptin resistance not only contributes to weight gain but may also lead to increased cardiac inflammation, greater fibrosis, hypertension, and impairment of the cardiac metabolism." (PMID 38397015, 2024). "Furthermore, previous studies have shown that high levels of leptin may affect blood pressure and contribute to hypertension mediated by sympathetic nervous system activation." (PMID 36950780, 2023). "Leptin is an adipokine that crosses the blood–brain barrier through a saturable transport system to reach the hypothalamus and activate the sympathetic nervous system and which may lead to hypertension." (PMID 36950780, 2023). "In the present study, we tested the hypothesis that elevated leptin plays a pathogenic role in SLE disease progression and promotes the development of autoimmune-associated hypertension and renal injury in the NZBWF1 mouse model of SLE, which has elevated leptin levels." (PMID 38031726, 2023). "In conclusion, our findings show that FLI were significantly increased in mild pre‐eclamptic pregnancies and allowed us to hypothesize that this rise might alter leptin bioavailability and bioactivity which might lead to the sympathetic hyperactivity and the hypertensive disorders during pregnancy." (PMID 36950780, 2023). "The hyperactivity of leptin in the neurons that retain leptin sensitivity may produce long-term deleterious effects, such as favoring an increased sympathetic tone that leads to hypertension and other cardiovascular problems." (PMID 35742928, 2022). "Furthermore, leptin appears to play a role in the development of hypertension." (PMID 35334523, 2022). "Taken together, these findings suggest hypertension and sympatho-excitation may occur through a manifest alteration to central leptin-melanocortin signaling pathways in the hypothalamus due mainly to maternal programming but also to a significant contribution from residual visceral fat." (PMID 34248679, 2021).
Hypertension (continued). "A high-fat-diet (HFD) pregnant rat model was used to investigate whether excessive intrauterine lipid exposure was associated with elevated blood pressure in offspring and increased levels of leptin, an important biomarker and mediator of vascular dysfunction and hypertension." (PMID 33431976, 2021). "This evidence may implicate leptin signaling in the pathogenesis of hypertension in NZO mice." (PMID 34276408, 2021). "The ventromedial hypothalamus (VMH) is a key area of integration and exposure to an obesogenic environment during early development may program the VMH of adult offspring to exhibit changes in the sensitivity to leptin and insulin, leading to hypertension and sympatho-excitation." (PMID 34248679, 2021). "Given that LEP is a master regulator of energy expenditure, the observations hint that placental insufficiency as a consequence of an energy imbalance may be a precursor to PE that is manifested as hypertension in mid to late gestation." (PMID 32126118, 2020). "Furthermore, a strong association has been reported between visceral adipose tissue and greater serum levels of cytokine, such as leptin, interleukin-6, plasminogen activator inhibitor-1, all of which are related both to endothelial dysfunction and hypertension." (PMID 31330870, 2019). "However, it is unknown to what extent leptin derived from adipose and/or placental tissues is involved in pregnancy-related hypertension." (PMID 31737362, 2019). "This study may not provide direct evidence that the expression of CYP17A1 influences hypertension because the lack of gene expression data, but our study demonstrated the associations of the SNP rs11191548 near CYP17A1 with HDL and leptin that contribute to hypertension." (PMID 29338791, 2018). "Adiponectin levels were negatively correlated with gestational BMI (r = −0.29, p = 0.013), and leptin levels positively correlated with prepregnancy BMI (r = 0.57, p < 0.0001), gestational BMI (r = 0.39, p = 0.0007), hyperglycemia (r = 0.31, p = 0.0086) and hypertension (r = 0.27, p = 0.0196)." (PMID 27651836, 2016). "Furthermore, to clarify which hypertension-related stress activates leptin and leptin receptor expression, we measured leptin and leptin receptor mRNA expression in isolated ventricular myocytes stimulated with angiotensin-II (ANGII), endothelin-1 (ET-1), or mechanical stretch." (PMID 23270329, 2012). "The strongest associations were detected between rs10954174 in Leptin (LEP) gene and DBP (P = 5.2×10−5, linear regression); between rs10889553 in Leptin receptor gene (LEPR) and SBP (P = 4.5×10−5, linear regression) as well as hypertension (P = 4.14×10−4, logistic regression)." (PMID 19562039, 2009). "In the non-geriatric group, the key determinants were the presence of hypertension, along with CRP, hemoglobin, hematocrit, and leptin levels." (PMID 40806940, 2025). "In contrast, in the non-geriatric group, well-being was most strongly influenced by the presence of arterial hypertension, as well as levels of CRP, hemoglobin, and leptin." (PMID 40806940, 2025). "Considering these uncertainties, this study aimed to determine whether elevated serum leptin levels are independently associated with vascular reactivity impairment, as assessed by the vascular reactivity index (VRI) obtained from digital thermal monitoring, in patients with hypertension." (PMID 41470134, 2025). "Key adipocytokines such as leptin, TNF-α, IL-6, and angiotensinogen contribute to hypertension by stimulating sympathetic SNS activity and impairing endothelial function." (PMID 40430185, 2025). "For example, leptin is an adipokine that elevates BP via central activation of the SNS, serving as a key mediator for obesity-related hypertension." (PMID 40356772, 2025). "Thus, hyperleptinemia and leptin resistance may be associated with negative health effects, including cardiovascular risk factors such as high blood pressure." (PMID 41572970, 2025).
Hypertension (continued). "It was also found that despite the lack of subcutaneous adipose tissue, and subsequently a lack of leptin, in individuals with lipodystrophy, congenital leptin deficiency, or biallelic leptin receptor gene variants some of those individuals still have hypertension." (PMID 37872379, 2024). "Additionally, RGT may reduce hypertension due to a reduction in serum leptin." (PMID 39598339, 2024). "Still, an increased expression of SVEP1, NRP1, RNASE1, QSOX1, and GKN1, along with decreased expression of XYLT2, CFH, LEP, and CETP serum levels were found in patients with hypertension." (PMID 37792298, 2023). "Particularly in obese males, increased leptin levels increase SNA to the muscle and kidneys, thereby contributing to hypertension development." (PMID 36769012, 2023). "Leptin injection raised ICAM-1 and Eseltin circulation concentrations, resulting in hypertension and proteinuria in pregnant rats." (PMID 36258174, 2022). "Leptin is also considered a uremic toxin, contributing to many CKD complications including cachexia, protein-energy wasting (PEW), insulin resistance, hypertension, cardiovascular disease, and bone pathologies." (PMID 36726470, 2022). "Bariatric surgery also improves metabolic disorders and hypertension due to increasing in GLP-1 secretion, decreasing leptin secretion and SNS activity, and changing gut microbiome composition." (PMID 36615704, 2022). "Positive correlations between leptin and increased carotid–femoral PWV have also been reported in patients with hypertension, coronary artery disease, chronic kidney disease patients in predialytic stages and also in hemodialysis patients." (PMID 34202323, 2021). "The goal of this research was to investigate the molecular mechanisms of hypertension-induced VSMC remodeling and the involvement of leptin and APN in this process." (PMID 32566092, 2020). "Recently, the CB was described to contribute to leptin-induced hypertension, since CSN denervation abolished the increase in mean arterial pressure induced by 3 days of subcutaneous administration of leptin in C57BL/6J mice." (PMID 32756352, 2020). "In this study, we investigated the molecular mechanisms of hypertension-induced VSMC remodeling and the involvement of leptin and APN in this process." (PMID 32566092, 2020). "Bariatric surgery improves metabolic disorders and hypertension due to increasing GLP-1 secretion, decreasing leptin secretion and SNS activity, and changing gut microbiome composition." (PMID 31236708, 2019). "Adipokines, including adiponectin and leptin, and renin-angiotensin-aldosterone system (RAAS) contribute to hypertension." (PMID 31236708, 2019). "Nevertheless, leptin has been demonstrated to upregulate RAS and pro-inflammatory cytokines and mediate angiotensin II-elicited hypertension after feeding rats a high-fat diet for 3 weeks." (PMID 29636702, 2018). "Leptin has been reported to upregulate RAS and pro-inflammatory cytokines, as well as to mediate angiotensin II-elicited hypertension in rats fed a high-fat diet for 3 weeks." (PMID 29636702, 2018). "In contrast, the proinflammatory actions of leptin and resulting oxidative tissue injury on the periphery escape central leptin resistance and exert its deleterious effects on SNA, hypertension, and cardiovascular neurologic and metabolic complications in OSA." (PMID 29675134, 2018). "Our results showed that leptin treatment increased Ang II plasma levels and progressively increased the SBP, achieving a pre-hypertension state." (PMID 25793389, 2015). "Serum levels of adipokines, including adiponectin, leptin, and resistin, have been reported to be involved in the development and progression of both T2DM and hypertension." (PMID 24414038, 2014). "Leptin and leptin receptor (LEPR) genes have been suggested to be candidate genes for hypertension via their direct effects on regulation of blood pressure (BP) and adipose tissue metabolism, or indirect effect on obesity." (PMID 24522342, 2014).
Hypertension (continued). "Free leptin index is calculated as the ratio between levels of circulating leptin and SLR, and correlates in healthy humans positively with body fat mass, plasma insulin and masked hypertension, and negatively with waist-hip ratio." (PMID 21118562, 2010). "Accumulated visceral adipose tissue produce and secrete a number of adipocytokines, such as leptin, tumor necrosis factor-α (TNF-α), interleukin-6 (IL-6), angiotensinogen, and non-esterified fatty acids (NEFA), which induce development of hypertension." (PMID 18416854, 2008). "Unlike adiponectin, leptin levels are elevated in individuals with obesity and CKD, which represents a greater risk of hypertension, inflammation, and fibrosis." (PMID 40724891, 2025). "Vasoconstriction, activation by leptin of the renin–angiotensin–aldosterone system (RAAS) and activation of the sympathetic nervous system (SNS), with subsequent renal sodium reabsorption, seem to account for the emergence of arterial hypertension." (PMID 40137089, 2025). "Leptin, acting on melanocortin four receptors (MC4R) in the paraventricular nucleus of hypothalamus (PVN), appears to be required for early-life programming of hypertension arising from either maternal obesity or neonatal hyperleptinemia." (PMID 40356772, 2025). "Adiposity-related pro-inflammatory markers such as leptin, interleukin-6 (IL-6), and tumour necrosis factor-α (TNF-α), and lower levels of anti-inflammatory markers, such as adiponectin play a role in the development of hypertension." (PMID 37872379, 2024). "Increased psychosocial stress in JSW workers may also lead to abnormal levels of catecholamines, cortisol, leptin, and GLP-1, as well as behavioural changes such as changes in dietary patterns, which may contribute to the development of T2DM and hypertension." (PMID 38803204, 2024). "However, alongside aging factors, the elevation of leptin increases sympathetic nerve activity and RAS activity in postmenopausal women and OVX animal models, contributing to postmenopausal hypertension." (PMID 39655343, 2024). "Among these genes, PKM and LEP were overexpressed in women older than 35 years old ( p<0.05; p<0.05); the expression of PKM, LEP, and HK2 differed remarkably in women with different BMI (all p<0.05); PKM overexpressed in women with hypertension (p<0.05)." (PMID 38166707, 2024). "Moreover, many studies showed how higher levels of leptin were found in the placentas of women with GDM and hypertension disorders." (PMID 38673471, 2024). "The production of leptin, one of the most well-studied adipokines in CVD, is significantly increased in obese patients, and the mechanisms by which it contributes to the development of hypertension show significant sex differences in young patients." (PMID 36012601, 2022). "Adipokines, including adiponectin and leptin, and the renin–angiotensin–aldosterone system (RAAS)may also contribute to hypertension." (PMID 36615704, 2022). "Using those models, we have confirmed that even without knowing age, BMI or hypertension status, we can reach relatively robust results using only AFs (71% accuracy on the test dataset using AFs without leptin)." (PMID 36505829, 2022). "Biologic explanations include differences in pathophysiological mechanisms for hypertension, such as enhanced Renin Angiotensin Aldosterone system (RAAS) activity with exaggerated renal sodium retention and increased leptin-induced sympathetic nervous system activation." (PMID 36570845, 2022). "Therefore, they concluded that in DIO rats, central interactions between leptin, the RAS (in particular AngII and AT1R), and inflammation set the stage for the hypertension induced by systemically administered AngII." (PMID 32160920, 2020). "LEP rs7799039may independently affect the incidence of CAD, whereas LEP rs2167270 may affect theincidence of CAD in concert with hypertension." (PMID 32049202, 2020).